LPL (lipoprotein lipase)
Diseases named in the same sentence as LPL in open-access papers (continued):
Sharing a sentence is not in itself a finding about the gene and the disease.
Crohn disease (2 papers, 2013 to 2023). A gastrointestinal disorder characterized by chronic inflammation involving all layers of the intestinal wall, noncaseating granulomas affecting the intestinal wall and regional lymph nodes, and transmural fibrosis. "However, serum C-reactive protein levels, disease duration, and the presence of an ileocolonic Crohn’s disease phenotype were found to be significantly and independently positively related to LPL." (PMID 36982268, 2023).
deficiencies (2 papers, 2024 to 2025). "Modulation of PLA2G12B activity may have particular therapeutic value for the treatment of familial lipase deficiencies, such as lipoprotein lipase (LPL) mutants." (PMID 38453914, 2024).
demyelinating disorders (2 papers, 2018 to 2020). "However, since altered abundance of LPL has been repeatedly implicated in AD and demyelinating disorders, metabolic diseases, and aging, it is likely that further study may reveal additional associations with functional LPL mutations." (PMID 33172164, 2020). "In summary, our findings highlight the importance of LPL in demyelinating disorders and are the first to demonstrate that microglial-LPL is directly involved in reparative processes needed for remyelination." (PMID 29599706, 2018). "We anticipate that the role of LPL in debris clearance and uptake may be exploited to develop future therapies for demyelinating disorders such as MS, and also primary neurodegenerative disease." (PMID 29599706, 2018).
endometriosis (2 papers, 2014 to 2025). The growth of functional endometrial tissue in anatomic sites outside the uterine body. "Some studies have shown that liver lipid synthesis and lipoprotein lipase activity may be inhibited in patients with endometriosis, resulting in triglyceride (TG) dysregulation." (PMID 40761347, 2025).
Familial hypertriglyceridemia (2 papers, 2017 to 2022). "By characterizing these two novel LPL mutations, this study has expanded our understanding on the pathogenesis of familial hypertriglyceridemia (FHTG)." (PMID 28548960, 2017). "Familial hypertriglyceridemia (F-HTG) is an autosomal dominant genetic disorder which is characterized by the overproduction of very low density lipoprotein (VLDL) from the liver and has been associated with the lipoprotein lipase gene (LPL)." (PMID 36138787, 2022).
fetal growth restriction (2 papers, 2015 to 2017). A fetus that does not grow beyond the 10th percentile of conventionally accepted weight for gestational age. "Effect of tributyrin on the activities of hepatic lipase (HL), lipoprotein lipase (LPL), and total lipase (TL) in the liver of piglets with intrauterine growth retardation (IUGR) (day 21)." (PMID 26317832, 2015).
Hypernatremia (2 papers, 2025). An abnormally increased sodium concentration in the blood. "A possible explanation is the increased hepatic secretion of triglycerides, which is caused by the inhibition of lipoprotein lipase by chronic hypernatremia." (PMID 40981014, 2025). "Lipoprotein lipase, an enzyme critical for clearing chylomicrons and very-low-density lipoproteins from circulation, is inhibited by hypernatremia." (PMID 40646895, 2025).
hyperparathyroidism (2 papers, 2016 to 2023). Hyperfunction of the parathyroid glands resulting in the overproduction of parathyroid hormone. "Hyperparathyroidism may impair the lipid elimination by decrease in lipoprotein lipase activity." (PMID 36890506, 2023).
Hypoalbuminemia (2 papers, 2024 to 2025). The concentration of albumin in the blood circulation is below the lower limit of normal. "It has been shown that lipoprotein lipase activity is reduced in hypoalbuminemia in the absence of proteinuria due to defective endothelial binding." (PMID 38720111, 2024). "While to our knowledge no studies have been performed in humans to investigate the pathophysiology of this association in non-nephrotic CKD, animal experiments have shown that hypoalbuminemia has a strong inhibiting effect on lipoprotein lipase, independent of proteinuria." (PMID 38720111, 2024).
hypogonadism (2 papers, 2012 to 2025). A disorder characterized by decreased function of the gonads. "In fact, hypogonadism is known to induce (a) a muscle mass reduction and visceral fat mass increase, (b) insulin resistance, and (c) an increase of the activity of lipoprotein lipase (LPL), the main enzymatic regulator of triglyceride uptake in the fat cell, preferentially in abdominal fat." (PMID 22235202, 2012).
insulinoma (2 papers, 2012 to 2023). "In INS-1 cells (clonal cells from a rat insulinoma cell line), high glucose levels stimulate the activity of LPL both in total cell extracts and in the heparin-releasable fractions of LPL that is secreted and associated to the cell surfaces." (PMID 23186339, 2012).
intestinal polyp (2 papers, 2017 to 2020). Discrete abnormal tissue masses that protrude into the lumen of the intestine. "On the other hand, the lipoprotein lipase activator NO-1886, peroxisome proliferator-activated receptor ligands and erythromycin have been shown to mainly reduce the numbers of intestinal polyps in the proximal part of the small intestine." (PMID 31963747, 2020). "LPL inducers NO-1886 and PPAR ligands have been shown to significantly reduce the number of intestinal polyps in the proximal part of the intestine." (PMID 28406434, 2017).
iron deficiency (2 papers, 2024 to 2025). "In lipid metabolism, magnesium deficiency reduces lipoprotein lipase activity, impairs very-low-density lipoprotein (VLDL) clearance and promotes free fatty acid release." (PMID 41245414, 2025). "A high-iron diet may raise triglyceride levels by reducing lipoprotein lipase activity, while iron deficiency may lower triglyceride levels by decreasing the activity of enzymes involved in fatty acid synthesis." (PMID 39685501, 2024).
ischemic stroke (2 papers, 2017 to 2025). A stroke disorder caused by obstruction of blood flow to the brain, due to thrombotic (local blood clot formation) or embolic (due to a blood clot or other material traveling from another site) event. "Previously, MR methods have been used to investigate the causal relationship of circulating protein biomarkers on ischemic stroke and the impact of angiopoietin-like protein 3 (ANGPTL3) and 4 (ANGPTL4) inhibition of lipoprotein lipase (LPL) on CVD." (PMID 40904650, 2025). "Four hundred eight patients with ischemic stroke and 347 unrelated healthy individuals of age and sex matched were genotyped for Apolipoprotein A5 (ApoA5), lipoprotein lipase (LPL), Cholesteryl ester transfer protein (CETP) and low-density lipoprotein receptor (LDL-R) genes." (PMID 28623937, 2017).
lymph node metastasis (2 papers, 2025). "The findings revealed notable variations in LPL mRNA expression across different stages of lymph node metastasis." (PMID 40427755, 2025).
malnutrition (2 papers, 2021 to 2025). Inadequate nutrition resulting from poor diet, malabsorption, or abnormal nutrient distribution. "Interestingly, SGMS1 deficiency has been linked to adipose tissue atrophy, reduced lipoprotein lipase activity, elevated plasma triglyceride levels, impaired fatty acid uptake, and malnutrition." (PMID 40005876, 2025). "Furthermore, results of the recent studies suggest that the genes involved in hepatic lipid synthesis (ACACA, FASN, LPL, SCD1, FADS1, and FADS2) were down-regulated over nutritional deficiency." (PMID 35111749, 2021).
nephrosis (2 papers, 2004 to 2011). Pathological processes of the KIDNEY without inflammatory or neoplastic components. "Several studies have revealed that peripheral catabolism of triglyceride-laden lipoproteins (i.e., CM and VLDL) is impaired and postheparin LPL activity and mass are reduced in clinical nephrosis." (PMID 21762526, 2011). "In addition, there are reports that in patients with nephrosis there are inhibitors of LPL in the circulating blood and that VLDL isolated from such patients are lipolyzed slowly by LPL." (PMID 15527497, 2004).
neuroblastoma (2 papers, 2013 to 2023). Neuroblastoma (NB) is the most common solid, extracranial childhood tumor. "Using a human neuroblastoma cell line and a Parkin knockout mouse model, we demonstrate that Parkin expression level positively correlates with neuronal LPL protein level and activity." (PMID 36519761, 2023). "To further investigate the effect of Parkin on LPL level, we employed SH-SY5Y neuroblastoma cell model with stable O/E of FLAG-tagged Parkin that we have previously reported." (PMID 36519761, 2023). "In vitro studies have shown presence of secreted LPL in conditioned media of human cortical neuronal cell line (HCN2) and neuroblastoma cells (SK-N-SH), but not in media of cultured primary human astrocytes." (PMID 24004859, 2013).
osteosarcoma (2 papers, 2015 to 2025). A usually aggressive malignant bone-forming mesenchymal neoplasm, predominantly affecting adolescents and young adults. "LPL activity has been reported in gastric and rectal cancers, malignant fibrous histiocytomas, and osteosarcomas, with the high proliferating outer area of rectal tumors and fibrous histiocytomas having an enhanced expression of LPL compared with the center." (PMID 25866768, 2015). "Recent studies on osteosarcoma involving the LCP1 gene (also known as actin-bundling protein L-plastin or LPL), have shown that the aberrant expression of LCP1 gene activates the JAK2/STAT3 signaling pathway, linking IL-6, IL-6R, and LCP1 in the context of tumor progression." (PMID 40759647, 2025).
overnutrition (2 papers, 2011 to 2021). An imbalanced nutritional status resulting from excessive intake of nutrients. "The greater impact of periconceptional overnutrition in the female lamb, may be related to the higher level of expression of adipogenic and lipogenic genes, for example, G3PDH and lipoprotein lipase (LPL) present in adipose tissue in female, compared to male lambs." (PMID 22203829, 2011).
peritonitis (2 papers, 2025). Inflammation of the peritoneum (tissue that lines the abdominal wall and covers most of the organs in the abdomen). "Conversely, Forkhead Box Protein O1 (FOXO1), Lipoprotein Lipase (LPL), and Tyrosine-protein Kinase Yes (YES1) were downregulated in peritonitis-afflicted animals when compared to the sham group." (PMID 40102905, 2025). "The group sampled 2 h following treatment exhibited a decrease in the concentrations of 35 proteins in animals subjected to laparoscopic lavage, while four proteins (TGFBR3, LPL, CCL2 and IL6) were found in elevated concentrations compared to time-matched peritonitis controls." (PMID 40102905, 2025).
prostate tumor (2 papers, 2012 to 2025). "The findings support the well-known role of NKX3.1 as a prostate tumor suppressor, while the LPL gene is often deleted alongside NKX3.1 due to their close proximity." (PMID 40563400, 2025).
rhabdomyolysis (2 papers, 2023 to 2025). Necrosis or disintegration of skeletal muscle often followed by myoglobinuria. "Fenofibrate (FEN) is an antilipidemic drug that increases the activity of the lipoprotein lipase enzyme, thus enhancing lipolysis; however, it may cause myopathy and rhabdomyolysis in humans." (PMID 37270716, 2023).
sarcoma (2 papers, 2024 to 2025). A usually aggressive malignant neoplasm of the soft tissue or bone. "Then, we analyzed the expression of biomarkers of osteoblasts (COL1A1, BGLAP and RUNX2), chondrocytes (COL2A1, COMP and SOX9) and sarcoma (POSTN and DCN), adipocyte (LPL and PPARG) and BMSCs." (PMID 39715773, 2024).
sarcopenia (2 papers, 2019 to 2025). Progressive decline in muscle mass due to aging which results in decreased functional capacity of muscles. "The genes identified in this study, namely CXCR1, CXCR2, and LPL, exhibit substantial potential as clinical diagnostic and therapeutic targets for sarcopenia." (PMID 40625358, 2025). "The research pinpointed three genes associated with chemokines and NETosis (CXCR1, CXCR2, LPL) and developed highly accurate diagnostic models, offering a new and preliminary approach to differentiate sarcopenia and its early stages." (PMID 40625358, 2025). "Univariate logistic regression showed that higher CXCR2 and CXCR1 expression increased sarcopenia risk, while lower LPL and IL18 expression was protective." (PMID 40625358, 2025). "By employing integrative bioinformatics strategies and multiple machine learning algorithms, we have successfully identified three signature chemokine- and NETosis-associated genes (CXCR1, CXCR2, and LPL) and constructed robust diagnostic models for sarcopenia detection." (PMID 40625358, 2025). "Consequently, the low expression of LPL may be associated with sarcopenia due to disorders of lipid metabolism and myosteatosis." (PMID 40625358, 2025). "Subsequently, an intersection of these three primary gene sets, as determined by univariate logistic regression, LASSO, and SVM-RFE models, led to the identification of three optimal signature genes—CXCR2, CXCR1, and LPL—for sarcopenia." (PMID 40625358, 2025). "To explore the roles of CXCR2, CXCR1, and LPL in sarcopenia-related pathways, we analyzed these genes individually using single-gene GSEA and GSVA." (PMID 40625358, 2025). "CXCR1 and CXCR2 levels were significantly higher, and LPL levels were lower in the sarcopenia group, consistent with the training group." (PMID 40625358, 2025). "In the sarcopenia group, LPL perturbation led to down-regulation of the PPAR signaling pathway, which is crucial for lipid and glucose metabolism and inflammatory responses." (PMID 40625358, 2025). "High CXCR1 and CXCR2 and low LPL levels may indicate sarcopenia progression, aiding early detection." (PMID 40625358, 2025). "In our study, we observed a significant down-regulation of LPL expression in the sarcopenia group." (PMID 40625358, 2025). "Understanding LPL’s dual role in metabolism and immunity could inform sarcopenia treatments by targeting metabolic and inflammatory pathways." (PMID 40625358, 2025). "However, research on LPL’s link to sarcopenia via inflammation is scarce, necessitating further studies." (PMID 40625358, 2025). "However, the relationship between LPL and GPIHBP1 and skeletal muscle mass, including sarcopenia, has not been fully understood." (PMID 30947712, 2019).
Senile plaques (2 papers, 2015 to 2021). Senile plaques are extracellular deposits of amyloid in the gray matter of the brain. "LPL accumulates in senile plaques, and its expression has been shown to be increased in the hippocampus of AD mice." (PMID 34836168, 2021). "Lipoprotein lipase (LPL) binds ApoE and LRP1, and has also been localized in senile plaques." (PMID 26263173, 2015).
Tangier disease (2 papers, 2018 to 2023). "Alaupovic first identified the LpAII:B complex particle in the plasma of patients with Tangier disease and showed that it differed metabolically from other TGRLP by being lipolysis resistant and a poor substrate for LPL." (PMID 29807532, 2018).
thalassemia (2 papers, 2020 to 2024). An inherited blood disorder characterized by a decreased synthesis of one of the polypeptide chains that form hemoglobin. "Thalassemia patients are more prone to infections, and TNF-α reduces lipoprotein lipase activity in adipose tissue." (PMID 39328659, 2024).
uremia (2 papers, 2016 to 2022). A clinical syndrome associated with the retention of renal waste products or uremic toxins in the blood. "An increased number of lipase inhibitors (apo C-III) in the setting of uremia may also play a role in the decrease in lipoprotein lipase-dependent TG-rich lipoprotein catabolism." (PMID 35683611, 2022).
acne vulgaris (1 paper, 2024). "Similarly, targeting the lowering of triglycerides through lipoprotein lipase (LPL) was significantly associated with an increased risk of acne vulgaris, indicated by an OR of 1.607 (95%CI: 1.124–2.299, p = 0.009)." (PMID 38903813, 2024).
adenovirus infection (1 paper, 2015). "Lipasin negatively regulates the activity of heparin releasable LPL in cardiac and skeletal muscles at the fed state, and therefore, it is possible that in mice with antibody injection or adenovirus infection, the phenotype in TAG metabolism is caused by changes in LPL activity in these tissues." (PMID 26687026, 2015).
amyotrophic lateral sclerosis (1 paper, 2024). Amyotrophic lateral sclerosis (ALS) is a neurodegenerative disease characterized by progressive muscular paralysis reflecting degeneration of motor neurons in the primary motor cortex, corticospinal tracts, brainstem and spinal cord. "The authors of this study proved that the progression of amyotrophic lateral sclerosis (ALS) leads to the activation of PPARγ in motor neurons, which contributes to the increase in the activity of lipid detoxifying enzymes, such as lipoprotein lipase and glutathione S-transferase α-2." (PMID 39062500, 2024).
androgen excess (1 paper, 2022). "Exposure to chronic androgen excess in women with PCOS was shown to suppress SAT lipolysis in some studies and to impair SAT lipoprotein lipase activity, which controls the delivery of fatty acids from circulating triglyceride-rich lipoproteins to AT." (PMID 35049520, 2022).
anemia (1 paper, 2021). A reduction in the number of red blood cells, the amount of hemoglobin, and/or the volume of packed red blood cells. "A study conducted in Quebec, Canada illustrated LPL deficiency with heterozygous genotype presenting as irritability, pallor, gastrointestinal bleed, anemia, and splenomegaly." (PMID 33419463, 2021).
aneurysmal disease (1 paper, 2019). "In this AAA gene list we identified previously AAA-associated genes COL11A1, ADIPOQ, and LPL, thus validating our approach as well as novel genes; CXCL13, SLC7A5, FDC-SP not previously linked to aneurysmal disease." (PMID 31683995, 2019).
aortic aneurysm (1 paper, 2021). A ruptured aneurysm located in the wall of the proximal portion of the descending aorta proceeding from the arch of the aorta. "A similar finding was noted for LPL variants on aortic aneurysms in the UK Biobank cohort (OR = 0.60, 95% CI = 0.43–0.83, p = 1.95 × 10−3), but this was not replicated in the FinnGen cohort (OR = 1.04, 95% CI = 0.79–1.38, p = 0.78)." (PMID 34834523, 2021).
aortic atherosclerosis (1 paper, 2021). A atherosclerosis that involves the aorta. "Apo‐CII and ‐CIII are considered as endogenous mediators of lipoprotein lipase activity and affect the concentration of triglycerides in blood which leads to aggravation of aortic atherosclerosis, thereby increasing the inflammatory response." (PMID 33381894, 2021).
artery stenosis (1 paper, 2011). "In fact, losartan improves lipid metabolism abnormality and increases LPL activity in adipose tissue of rats with renal artery stenosis." (PMID 21762526, 2011).